ANXA1 (annexin A1)
Diseases named in the same sentence as ANXA1 in open-access papers (continued):
Sharing a sentence is not in itself a finding about the gene and the disease.
lung fibrosis (8 papers, 2011 to 2024). "For example, ANXA1 is reported to have anti-inflammation activity in lung endothelial cells and is able to prevent lung fibrosis." (PMID 37246643, 2023). "This idea was further supported by a study in which the antibodies to ANXA1 were detected in the serum and bronchoalveolar lavage fluid of patients with acute exacerbations of idiopathic pulmonary fibrosis (IPF)." (PMID 36225941, 2022). "Here we have applied the bleomycin lung fibrosis model to AnxA1 null mice over a 21-day time-course, to monitor potential impact of this mediator on the control of the inflammatory and fibrotic phases." (PMID 22011168, 2011). "Against this background, the present study was undertaken to compare cellular, tissue and macroscopic alterations observed in the model of bleomycin-induced lung fibrosis in wild type and AnxA1 null mice." (PMID 22011168, 2011). "Evidence suggests that the endogenous protein AnxA1 may downregulate pulmonary fibrosis, since AnxA1-null mice show excess ECM deposition after stimulation with bleomycin and crystalline silica particles." (PMID 35269381, 2022). "Together these data show a pathophysiological relevance for ANXA1 in lung inflammation and in fibrosis, and may open up a new approach for the pharmacological handling of pneumonia and lung fibrosis." (PMID 32887260, 2020). "Moreover, there was a statistically significant difference (+23.5% at day 7; +20% at day 21) between wild type and AnxA1 null bleomycin-treated mice, indicating induction of a higher degree of pulmonary fibrosis in the latter genotype." (PMID 22011168, 2011). "Collectively these data reveal a pathophysiological relevance for endogenous AnxA1 in lung inflammation and, more importantly, fibrosis, and may open new insights for the pharmacological treatment of lung fibrosis." (PMID 22011168, 2011).
ulcerative colitis (8 papers, 2012 to 2025). An inflammatory bowel disease involving the mucosal surface of the large intestine and rectum. "A previous study found the high expression of anti-ANXA1 autoantibodies in patients with ulcerative colitis and Crohn’s disease and a direct correlation of the potency of the antibodies with disease activity." (PMID 36225941, 2022). "In ulcerative colitis, Annexin A1 upregulation is a feature of subjects in remission, thereby suggestive of a significant role in promoting mucosal homeostasis." (PMID 35563776, 2022). "AnxA1 expression is increased in intestinal tissue of ulcerative colitis patients while decreased in Crohn's disease patients, evidencing these diseases deregulate AnxA1 actions leading to compromised anti-inflammatory responses." (PMID 33519451, 2020). "ANXA1 expression is decreased in the subcellular fraction of intestinal epithelial cells from patients with ulcerative colitis as compared to healthy controls, while other studies found an increase in ANXA1 expression." (PMID 24130820, 2013). "Through the establishment of ulcerative colitis animal models combined with RNA-seq and ASTRAL-DIA proteomic analyses, we validated that specific hub genes, including Anxa1, Cd93, and Mfge8, exhibited consistent alterations at both the transcriptional and protein levels." (PMID 41050686, 2025).
astrocytoma (7 papers, 2013 to 2025). "In human astrocytomas, ANXA1 was shown to be abundantly upregulated in both the cytoplasm and nuclei of the tumor cells." (PMID 38639785, 2024). "ANXA1 is also known to be involved in proliferation, differentiation and apoptosis, serves as a substrate for EGFR, and is implicated in tumor progression of astrocytoma." (PMID 31952211, 2020). "Increased ANXA1 transcript levels were also observed in GBM and anaplastic astrocytoma tumours compared to normal tissue and high ANXA1 expression identified a group of astrocytoma and GBM patients with reduced survival." (PMID 27770278, 2017). "Triple immunofluorescence analysis of additional patient samples revealed elevated levels of ANXA1 protein in GFAP+ cells but not in CD31+ blood vessels in GBM samples in comparison to G.2 and G.3 astrocytoma samples." (PMID 41366031, 2025).
Crohn disease (7 papers, 2013 to 2023). A gastrointestinal disorder characterized by chronic inflammation involving all layers of the intestinal wall, noncaseating granulomas affecting the intestinal wall and regional lymph nodes, and transmural fibrosis. "Herein, we demonstrate that higher levels of colonic formyl peptide receptor 1 and annexin A1 correlate with histological recovery in Crohn’s disease patients under remission." (PMID 34603288, 2021). "In Crohn's disease, AnxA1 biosynthesis is dysregulated and higher levels correlate with successful intervention with biologicals against TNF-α." (PMID 31396220, 2019). "In another study in Crohn's Disease, AnxA1 is involved in intestinal homeostasis after anti-TNF-α treatment and suggested as a potential biomarker of therapeutic efficacy of anti-TNF-α treatment." (PMID 31396220, 2019). "This and other evidence suggests that ANXA1 auto-antibody levels were directly related to clinical disease in patients with Crohn's disease." (PMID 24130820, 2013). "We report a substantial loss of ANXA1 expression in the colonic mucosal and peripheral blood compartments from patients with progressive IBD, specifically Crohns Disease." (PMID 24130820, 2013). "It has been reported AnxA1 also plays a role on healing of damaged intestinal epithelium on murine IBD models, and that its expression is correlated with better prognosis on Crohn's disease patients." (PMID 33519451, 2020).
endotoxemia (7 papers, 2011 to 2021). "In an endotoxemia model, AnxA1-deficient mice showed a marked increase in the production of the pro-inflammatory cytokines interleukin (IL)-6 and tumor necrosis factor (TNF)-α, as well as exacerbated organ damage and mortality." (PMID 28809781, 2017). "A study using an experimental model of endotoxemia induced by bacterial lipopolysaccharides demonstrated an early rise in the level of ANXA1-SER in response to inflammatory stimuli." (PMID 24782913, 2014). "One such investigation showed increased promoter activity of the ANXA1 gene in lung epithelial cells at 6 h after induction of endotoxemia in mice." (PMID 22740770, 2012). "Western blot analysis showed from the animal level that in animals with endotoxemia, propofol can increase the expression of Annexin A1 in blood mononuclear cells, which is in line with the result of two-dimensional electrophoresis." (PMID 22164217, 2011). "To conclude, the results of our study clearly show that propofol can up-regulate the expression of Annexin A1 in rats with endotoxemia and LPS-stimulated THP-1 and the increased expression of Annexin A1 can also reduce the release of inflammatory factors." (PMID 22164217, 2011). "The data suggest that calves with high levels of annexin A1 may be better able to control neutrophil infiltration and promote neutrophil apoptosis in the lung, which could prevent neutrophil-induced lung injury and dampen the systemic consequences of endotoxemia." (PMID 23565988, 2013). "On one hand AnxA1 or peptide Ac2-26 treatment, in the case of LPS-induced endotoxemia, inhibited TNF-α release, whereas in the absence of AnxA1, increased levels of the cytokine was observed." (PMID 23497133, 2013). "After detection using ELISA and Western blot assays, it has also been found that propofol can not only promote the expression of Annexin A1, but also inhibit the phosphorylation level of p38 and release of inflammatory factors (IL-1β, IL-6 and TNF-α) in rats with endotoxemia." (PMID 22164217, 2011).
Nephropathy (7 papers, 2018 to 2024). A nonspecific term referring to disease or damage of the kidneys. "In a model of Adriamycin-induced nephropathy, the authors observed a time-dependent increase in glomerular AnxA1 expression with maximum levels in podocytes and parietal epithelial cells at d7 and d14 after induction." (PMID 36311242, 2022). "Renal expression of AnxA1 and its regulation in kidney disease have been studied in considerable detail." (PMID 36311242, 2022). "Notably, among these abnormally expressed proteins, 19 proteins were reported as kidney disease markers (Ada, Ambp, Anxa1, B2m, Camp, Col1a1, Cp, Ggt1, Glb1, Lgfbp7, Lifr, Lpl, Plau, Ptgds, S100a8, Serpinc1, Serpina3k, Tff1, and Vtn) (highlight in green)." (PMID 31708494, 2019). "Indeed, ANXA1 attenuates microvascular complications (nephropathy and cardiomyopathy) through restoration of Akt signalling in a murine model of Type I Diabetes Mellitus (T1DM)." (PMID 29614751, 2018). "In addition, ANXA1 shows protective roles in various renal diseases." (PMID 35783659, 2022). "Treatment with ANXA1 could hold therapeutic potential in other fibrosis-driven diseases such as kidney disease, whereby ANXA1 in renal fibroblasts reduces α-SMA and collagen A1 gene expression due to inhibition of TGF-β induced signalling and cytokine production." (PMID 29614751, 2018). "Patients with type 1 diabetes, irrespective of nephropathy, displayed increased plasma Annexin A1." (PMID 34943928, 2021).
allergic conjunctivitis (6 papers, 2016 to 2025). "IGF-1, Annexin A1, and Bcl2 were chosen as biomarkers in this study because of their important roles in inflammatory and apoptotic pathways associated with allergic conjunctivitis." (PMID 39934562, 2025). "Annexin A1, an anti-inflammatory mediator, controls the movement of white blood cells and helps inflammation go away, directly addressing the inflammatory processes that lead to allergic conjunctivitis." (PMID 39934562, 2025). "In conclusion, our findings demonstrate that the glucocorticoid effector protein AnxA1 has potential in prevention or as a new treatment for dry eye, allergic conjunctivitis and other forms of ocular surface inflammation through its effect on conjunctival goblet cells." (PMID 33968020, 2021). "In contrast, intense expression of both fprs were detected in conjunctival epithelial cells in an allergic conjunctivitis model, but the lack of AnxA1 protein in the ovalbumin-sensitized mice produced a marked increase only in fpr2 expression." (PMID 34831393, 2021).
clear cell renal carcinoma (6 papers, 2012 to 2024). A malignant epithelial neoplasm of the kidney characterized by the presence of lipid-containing clear cells within a vascular network. "We found that the expression level of ANXA1/2/4/5/6/7/8/13 in clear renal cell carcinoma tissue was higher than that in the kidney tissue, while the expression level of ANXA3/9/11 in the former was lower than that in the latter." (PMID 39290334, 2022). "Knockdown of Annexin A1 in Caki-2 cells (a human clear cell renal cell carcinoma line) resulted in reduced proliferation, invasion, motility and adhesion compared to control cells." (PMID 34943928, 2021). "ANXA1 is linked to sensitivity to TKIs, and in clear cell renal cancer (CCRC), YTHDC1, a reader of the m6A modification, interacts with ANXA1 mRNA via the m6A modification, reducing its stability, thereby inactivating the MAPK signaling pathway and rendering CCRC cells sensitive to TKIs." (PMID 39624079, 2024). "Importantly, Annexin A1 expression increased with the progression of clear cell renal cell carcinoma (and other cancer types), suggestive of its potential role in tumorigenesis." (PMID 34943928, 2021). "In clear cell renal cell carcinoma, the YY1/HDAC2 complex reduces the expression of YTHDC1, which modulates the sensitivity of ccRCC to sunitinib by targeting the ANXA1-MAPK pathway." (PMID 37495623, 2023).
cognitive deficits (6 papers, 2017 to 2025). "Results showed that ANXA1 levels were reduced in septic mice, and its deficiency exacerbated cognitive impairment and survival rate reduction." (PMID 39727329, 2024). "In 2022, a study rescued synaptic damage and cognitive impairment caused by transient ischemic attack (TIA) with a multiple mild stimulation (MMS) technique, which was closely related to the presence of ANXA1." (PMID 41208642, 2025). "ANXA1 KO mice exhibit greater inflammation, larger infarct volume and worse cognitive impairment than controls." (PMID 37208759, 2023). "Studies have found that ANXA1 in microglia promotes the binding of CX3CR1 in microglia to CX3CL1 in neurons during TIA, reduces the density of dendritic spines, and leads to synaptic damage and cognitive impairment caused by TIA." (PMID 41208642, 2025). "The decreased expression of ANXA1 in patients with mild cognitive impairment and AD might contribute to the increased neuroinflammation and cognitive deficits." (PMID 34105114, 2021). "Our study revealed that ANXA1 had decreased expression in patients with MCI and AD, indicating that a lower level of ANXA1 might contribute to the increased degree of neuroinflammation and cognitive impairment." (PMID 32308643, 2020). "However, its role in TIA is more complex, with findings suggesting that ANXA1 may contribute to synaptic damage and cognitive impairment." (PMID 41208642, 2025). "Extended exposures to anesthesia, such as sevoflurane, without surgical manipulation downregulated ANXA1 expression in endothelial cells, which contributed to cognitive deficits." (PMID 28912778, 2017). "Given these pro-resolving actions of ANXA1 in cerebrovascular disease, its reduction in the hippocampus of our HF-fed females could contribute to the worse vascular outcomes (lower CBF) and hippocampal-dependent cognitive deficits we previously observed." (PMID 37208759, 2023).
cystic fibrosis (6 papers, 2009 to 2022). Autosomal recessive disorder caused by pathogenic variants in the CFTR gene (cystic fibrosis transmembrane conductance regulator), which encodes a chloride and bicarbonate channel expressed in epithelial cells, and follow the diagnosis criteria. "In this context, deficiency of Annexin A1 reportedly worsens the phenotype of cystic fibrosis, a condition characterized by abnormal fluid transport across secretory epithelia and chronic inflammation involving the lung, pancreas, and intestine." (PMID 35563776, 2022). "ANXA1 levels in bronchoalveolar lavage fluids were higher in smokers and patients with cystic fibrosis." (PMID 29301525, 2018). "Of interest in the context of lung inflammation, down-regulation of endogenous AnxA1 expression has been noted in the bronchoalveolar lavage (BAL) fluid of cystic fibrosis patients." (PMID 22011168, 2011). "We have previously shown the association of ANXA1 expression with that of CFTR, the multifactorial protein mutated in cystic fibrosis." (PMID 19847291, 2009). "A form of ANXA1 with a molecular weight of 33 kDa is released rather than the 37 kDa ANXA1, suggesting that ANXA1 be degraded in smokers and patients with cystic fibrosis." (PMID 29301525, 2018).
endometrial cancer (6 papers, 2014 to 2024). Primary or metastatic malignant neoplasm involving the endometrium (mucous membrane that lines the endometrial cavity). "More importantly, we also here demonstrate that the increase on proliferation, invasion and migration of ECC-1 endometrial cancer cells upon depletion of C1GALT1 was associated to the overexpression of ANXA1." (PMID 36745330, 2023). "Therefore, although other players would also be responsible of these effects, we were able to demonstrate the causal correlation between C1GALT1 and ANXA1 protein expression with tumorigenic and metastatic properties of endometrial cancer cells." (PMID 36745330, 2023). "Collectively, these results correlate C1GALT1 and ANXA1 protein expression with tumorigenic and metastatic properties of endometrial cancer ECC-1 cells." (PMID 36745330, 2023). "With respect to ANXA1, it is a target of HSA-miR196a and the expression of hsa-miR-196a is inversely correlated with ANXA1 expression in esophageal, breast and endometrial cancer cell lines." (PMID 25536365, 2014). "Therefore, we hypothesized that the upregulation of ANXA1 upon C1GALT1 depletion could be associated to the increase in proliferation, invasion and migration of ECC-1 endometrial cancer cells." (PMID 36745330, 2023).
gastric adenocarcinoma (6 papers, 2013 to 2022). "Further, loss of Annexin A1 is a frequent and early event during head and neck carcinogenesis, while increased mucosal Annexin A1 expression is reported for gastric adenocarcinoma." (PMID 35563776, 2022). "In gastric adenocarcinoma tissues, ANXA1 is expressed in both the cytoplasm and the nucleus, and its nuclear location correlates with the advanced stage of the disease and peritoneal dissemination." (PMID 35805141, 2022). "While in gastric adenocarcinoma AnxA1 showed positive nuclear staining correlated with advanced disease stage and peritoneal dissemination but in normal tissues was predominantly localized in the cytoplasm." (PMID 23431236, 2013). "Similar studies showed that ANXA1 is expressed in both gastric adenocarcinoma and normal tissues." (PMID 35805141, 2022). "Finally, we performed immunohistochemistry for HIF-1α and ANXA1 on a tissue microarray comprising 397 samples of human gastric adenocarcinoma." (PMID 26760764, 2016). "This scenario prompted us to investigate the relationship between the gene and protein expression of annexin-A1 (ANXA1/AnxA1) and galectin-1 (LGALS1/Gal-1) in an inflammatory gastric lesion as chronic gastritis (CG) and gastric adenocarcinoma (GA) and its association with H. pylori infection." (PMID 23431236, 2013). "Moreover, ANXA1 and MYC tended to co-occur in the same stomach adenocarcinoma samples at the gene expression level (odds ratio between 2 and 10)." (PMID 26760764, 2016).
gout (6 papers, 2018 to 2025). A condition characterized by painful swelling of the joints, which is caused by deposition of urate crystals. "Furthermore, cluster 3 exhibited high expression of ANXA1, which inhibits phospholipase A2 and has been associated with antiinflammatory activity in gout." (PMID 38063198, 2023). "In a murine model of gout, for instance, ANXA1 was shown to promote neutrophil apoptosis and acute inflammation resolution, being essential to control chronic inflammation associated with gout." (PMID 41200163, 2025). "Annexin A1 plays a crucial role on resolution of inflammation in a model of gout by increasing neutrophil apoptosis." (PMID 36496970, 2022). "Pharmacologic or genetic inactivation of annexin A1 resulted in insufficient resolution of gout-related inflammation in mice." (PMID 32296442, 2020). "Annexin A1 levels are increased in the resolution phase of monosodium urate crystal–induced arthritis, a model of gout." (PMID 32296442, 2020). "Moreover, ANXA1 is involved in the resolution of neutrophil-mediated inflammatory responses during Leishmania braziliensis infection and in murine gout." (PMID 29544524, 2018).